SLC7A11 (solute carrier family 7 member 11)
Diseases named in the same sentence as SLC7A11 in open-access papers (continued):
Sharing a sentence is not in itself a finding about the gene and the disease.
tumor (continued). "On the other hand, hypoxia can promote HIF1α-mediated transcription of lactate dehydrogenase (LDH) and SLC7A11, activate intracellular lactate accumulation and cystine uptake, and promote tumor resistance to ferroptosis through the lactate/GPX4 pathway." (PMID 40855044, 2025). "SLC7A11 has been identified as playing a significant role in various aspects of tumor progression, including tumorigenesis, proliferation, metastasis, prognosis, and chemoresistance." (PMID 39569390, 2025). "Subcutaneous transplantation of NCI‐H2122 cells with SLC7A11 knockdown led to significantly reduced tumor growth and weight compared to control groups." (PMID 41030277, 2025). "Among these, ASCT2, GLS1, LAT1, SLC7A11, SLC3A2, and SHMT2 are key regulators of amino acid metabolism and have been implicated in tumour progression, therapy resistance, and immune evasion." (PMID 41154605, 2025). "Across diverse tumor entities, the transcriptional upregulation of SLC7A11 confers robust protection against oxidative insults, driving both malignant cell survival and therapeutic resistance." (PMID 40890129, 2025). "Extensive evidence supports BTG2’s tumor suppressor function via downregulation of SLC7A11 (a critical ferroptosis mediator) thereby modulating cellular susceptibility to oxidative stress." (PMID 41188368, 2025). "The growth curve plotted every 5 days revealed a stark contrast between the two groups, emphasizing the impact of SLC7A11 knockdown on tumor development." (PMID 41030277, 2025). "For example, a hypoxic tumor micro-environment can mediate tumor cell ferroptosis resistance by activating HIF1α and upregulating various anti-ferroptosis molecules such as SLC7A11, GPX4, TFRC and FTH115-17." (PMID 41049011, 2025). "In vivo and clinical data supported the positive roles of the METTL3/SLC7A11 axis in tumor growth and progression." (PMID 39800682, 2025). "SLC7A11 is frequently found to be overexpressed in various types of cancer, which plays a significant role in promoting tumor growth." (PMID 40535572, 2025). "GPX4 detoxifies lipid peroxides, protecting both tumor and immune cells from ferroptotic damage, whereas SLC7A11 maintains cystine uptake and glutathione biosynthesis, providing a metabolic safeguard." (PMID 41562065, 2025). "The effectiveness of the combined treatment was further demonstrated by xenograft studies, evidencing a significant decrease in tumor weight and volume associated with an enhanced expression of GPX4 and SLC7A11 in response to TAZ." (PMID 40229247, 2025). "METTL3 KD increases the expression of SLC7A11, further suppressing the erastin sensitivity of tumor cells in vivo." (PMID 39800682, 2025). "Growing evidence also suggests that targeting SLC7A11 is a promising approach in cancer therapy by effectively inhibiting tumor proliferation, invasion, and metastasis, as well as counteracting cancer stem cells and overcoming chemoresistance." (PMID 39569390, 2025). "In many malignancies, upregulation of SLC7A11 expression contributes to tumor cell resistance to ferroptosis, which promotes tumor growth, metastasis, and drug resistance." (PMID 40469292, 2025). "Given that ATF4 has been implicated in regulating SLC7A11 and SLC3A2 expression in both tumor and immune cells, we focused on ATF4 for further mechanistic studies." (PMID 41042068, 2025). "Results of the present study also demonstrated that SLC7A11 promoted the adaptation of NSCLC cells to TAM2 polarization in the tumor microenvironment." (PMID 40417819, 2025).
tumor (continued). "For instance, the cystine/glutamate antiporter SLC7A11 holds an important role in ferroptosis regulation, and the overexpression of SLC7A11 enhances tumor growth and promotes cancer escape from ferroptosis via regulating GSH production and lipid peroxidation." (PMID 40963919, 2025). "Combining ferroptosis induction with anti-PD-1/PD-L1 therapy seeks to exploit complementary biology: ferroptosis can increase antigen release and DAMPs, while ICIs sustain CTL function that further downregulates tumor SLC7A11 via IFN-γ." (PMID 41301464, 2025). "EIF2S1 controls GPX4 and SLC7A11 expression to protect tumor cells from ferroptosis, thus promoting tumor growth." (PMID 40302793, 2025). "We also elucidated the crucial function of the SLC7A11AR/miR-150-5p/SLC7A11 axis in facilitating tumor growth by suppressing ferroptosis, thereby presenting novel diagnostic and prognostic targets for the future treatment of LUAD." (PMID 40765833, 2025). "Specifically, IFN–γ released from ICI–activated CD8+ T cells downregulates system xc– components (SLC3A2 and SLC7A11) in tumor cells, thereby promoting lipid peroxidation and ferroptosis." (PMID 40895556, 2025). "Further analysis of SLC7A11 expression across various cancer types revealed that its expression was higher in most tumor tissues compared to normal tissues." (PMID 40378782, 2025). "Immunofluorescence-stained tumor sections confirmed the suppression of SLC7A11 and SLC3A2 expression in all medication groups." (PMID 40367177, 2025). "Previous studies also investigated that BAP1 links ferroptosis to tumor suppression by repressing SLC7A11 expression through BAP1-mediated H2Aub deubiquitination on SLC7A11 in PDAC cells." (PMID 40083694, 2025). "This study elucidates the mechanism underlying Nrf2-driven tumor progression in ATC, identifying BCL-2 and SLC7A11 as key transcriptional mediators of anoikis resistance." (PMID 41212415, 2025). "In ATC, which often displays immune infiltration, interferon-γ secreted by CD8+ T cells has been shown to downregulate SLC7A11, thereby promoting ferroptosis in tumor cells." (PMID 41294853, 2025). "Overall, the roles of METTL3 and METTL14 in regulating GPX4 and SLC7A11 are central to current research on m6A methyltransferase-mediated ferroptosis and its impact on tumor growth." (PMID 40271153, 2025). "Targeting SLC7A11 can enhance tumor cell sensitivity to treatment, overcome resistance, and improve therapeutic outcomes." (PMID 40012016, 2025). "By analyzing the TCGA patient database, it has been found that SLC7A11 mRNA expression is significantly higher in tumor tissues than in normal tissues across most cancer types." (PMID 39569390, 2025). "Our previous studies have confirmed that BAP1 represses SLC7A11-mediated cystine metabolism and promotes ferroptosis-dependent tumor suppression." (PMID 41310183, 2025). "LUAD EAM Sub-cohort: Altered antiporter activity, especially the cystine/glutamate antiporter SLC7A11, supports redox homeostasis and therapy resistance, linking transporter up-regulation to tumor growth and metastatic potential in NSCLC." (PMID 41228248, 2025). "Correlatives: serial stool metagenomics/metabolomics, tumor biopsies for SLC7A11/GPX4/FSP1 expression and BODIPY lipid peroxidation assays, and peripheral immune phenotyping." (PMID 41301464, 2025).
tumor (continued). "In turn, upregulation of SLC7A11/xCT was positively correlated with upregulation of Nrf2’s downstream targets, including Osgin1, and negatively correlated with tumor cell apoptosis." (PMID 40149945, 2025). "In contrast, in non-tumor diseases, chronic microenvironments induce compensatory cystine metabolism imbalance through epigenetic modifications (e.g., NFATc1 activation of SLC7A11), ​​creating conditions that promote pro-inflammatory immune cell infiltration." (PMID 41229417, 2025). "By continuously delivering GOx to the tumor microenvironment, NADPH is depleted, inducing disulfidptosis in SLC7A11-high tumor cells." (PMID 40358287, 2025). "This suggests potential modulation by tumor-specific factors such as epigenetic states or co-regulators, warranting further investigation into auxiliary mechanisms fine-tuning SLC7A11 and ALOX12 activity." (PMID 40696490, 2025). "This platform integrates MRI-guided tumor localization with ferroptosis induction, achieved through SLC7A11 downregulation, which reduces glutathione synthesis, amplifying lipid peroxidation and iron-dependent cell death." (PMID 41029459, 2025). "The results demonstrated that while treatment with either low-dose ZK53 or IKE alone did not significantly inhibit tumor growth, ZK53 markedly enhanced tumor sensitivity to SLC7A11 inhibition." (PMID 41357605, 2025). "SLC7A11 (also known as xCT) is a cystine/glutamate antiporter that is highly expressed in tumor cells and is an important pathway for cancer cell survival." (PMID 40104507, 2025). "Tumor cells, due to high expression of SLC7A11, develop “cystine addiction,” where NADPH depletion leads to reduced cystine metabolism and disulfide-mediated cytoskeletal collapse." (PMID 41229417, 2025). "Decreases SLC7A11 expression through demethylation, promoting ferroptosis, inhibiting tumor invasion & metastasis." (PMID 40740874, 2025). "Histological examination of excised tumors further confirmed that silencing SLC7A11 resulted in reduced cellular density within the tumors, which translated into smaller tumor sizes." (PMID 41030277, 2025). "For example, in a melanoma model, Treg infiltration significantly reduced tumor cell SLC7A11 expression, leading to resistance to ferroptosis." (PMID 40535125, 2025). "The latest research has found that CAFs can inhibit ferroptosis by regulating iron metabolism, promoting glutathione synthesis, and upregulating SLC7A11 (xCT) expression in tumor cells." (PMID 40959080, 2025). "Functional evidence indicates that targeting SLC7A11 can inhibit the proliferation and invasion of OS cells by triggering ferroptosis, highlighting its critical role in tumor progression." (PMID 41343099, 2025). "Research has demonstrated that SLC7A11 inhibits ferroptosis, which increases tumor growth in addition to HCC cell proliferation." (PMID 40465746, 2025). "Beyond genetic and epigenetic alterations, amino acid transporter-driven metabolic reprogramming—mediated by LAT1 (SLC7A5), ASCT2 (SLC1A5), and xCT (SLC7A11)—supports tumor proliferation, redox homeostasis, and immune escape." (PMID 41226775, 2025). "The development of engineered BEVs as a means to deliver SLC7A11 siRNA provides a novel approach to combat tumor progression and metastasis." (PMID 41030277, 2025).
tumor (continued). "While the expression of SLC7A11 in tumor tissue was significantly greater than that in normal tissue according to the TCGA database." (PMID 39800682, 2025). "For instance, the SLC7A11 inhibitor sulfasalazine restores tumor cell sensitivity to platinum-based drugs by increasing lipid peroxidation levels in colorectal cancer." (PMID 41235254, 2025). "Recent researches have indicated a significantly lower expression of SLC7A11 in tumor-infiltrating CD8+T cells compared to tumor cells, suggesting a disadvantage for CD8+T cells in competing for cystine." (PMID 40169575, 2025). "The SLC7A11/GPX4 pathway is classic for regulating ferroptosis and is closely associated with tumor progression." (PMID 41516285, 2025). "The GUL@LsiYY1@MZ nanosystem utilizes AMF-triggered release to downregulate SLC7A11, inducing ferroptosis and contributing to enhanced anti-tumor efficacy." (PMID 41029459, 2025). "For example, metformin alone has been reported to decrease SLC7A11 protein stability by inhibiting its UFMylation, and metformin combined with sulfasalazine can cooperatively induce ferroptosis and suppress tumor growth in the breast cancer model." (PMID 39569390, 2025). "The loss of tumor suppressor genes, mutations in oncogenes, or the overexpression of pro-tumor proteins elevates levels of SLC7A11 in cancer, resulting in the inhibition of ferroptosis and enhanced tumor progression." (PMID 40136455, 2025). "Inhibition of the anti-ferroptosis factor SLC7A11/SLC3A2 upregulates PD-L1 expression in tumor cells via IRF4/EGR1." (PMID 41373022, 2025). "In summary, our study demonstrates the protective effect of the ER stress response on glucose limitation‐induced disulfidptosis in SLC7A11‐high tumor cells." (PMID 39739602, 2025). "The expression levels of ACSL4 and SLC7A11 are important biomarkers for determining the ferroptosis sensitivity of CCA cells, with high expression often associated with tumor progression and poor prognosis." (PMID 41201667, 2025). "SLC7A11 promotes HCC metastasis by increasing programmed death ligand 1 and colony-stimulating factor 1, and its high expression is linked to poor tumor differentiation and an advanced tumor-node-metastasis stage 25." (PMID 39744421, 2025). "In non-small cell lung cancer (NSCLC), PRKAA2 enhances tumor growth and suppresses ferroptosis via the SLC7A11/GSH/GPX4 pathway." (PMID 40575157, 2025). "Most tumor cells in vivo rely primarily on SLC7A11 to translocate extracellular cystine into the cytoplasm and reduce it to Cys in the presence of NADPH." (PMID 40295497, 2025). "The therapeutic potential of targeting SLC7A11 is immense, offering promising strategies for inhibiting tumor progression at multiple stages." (PMID 39569390, 2025). "The generation of these tumor models provided crucial insight into the role of SLC7A11 in vivo, demonstrating its contribution to tumor growth dynamics." (PMID 41030277, 2025). "This interaction promotes the stabilization and expression of SLC7A11, thereby supporting ferroptosis resistance and tumor growth, emphasizing the critical role of the CD44/OTUB1-SLC7A11 pathway." (PMID 40259468, 2025). "SLC7A11, a critical component of the cystine/glutamate antiporter system Xc-, plays an increasingly recognized role in neoplastic disease." (PMID 40297144, 2025). "GOx can induce disulfidptosis in tumor cells and tissues with high SLC7A11 expression, effectively inhibiting tumor recurrence." (PMID 40358287, 2025).
tumor (continued). "This over-reliance on a single transporter (SLC7A11) provides a clear therapeutic window, as inhibiting it has a far more negligible impact on normal cells than on tumor cells." (PMID 41201667, 2025). "Activated CD8+ T cells secrete interferon-γ (IFN-γ), which can downregulate tumor SLC7A11 expression and thereby sensitize tumor cells to ferroptosis (the “IFN-γ–SLC7A11–ferroptosis” axis)." (PMID 41301464, 2025). "WB analyses revealed a significant decrease in SLC7A11 expression in NSC48160‐treated tumor tissues in a dose‐dependent manner." (PMID 40390765, 2025). "Inhibition of SLC7A11 or GPX4 with ferroptosis inducers can increase the sensitivity of radioresistant tumor cells and xenografts to radiotherapy." (PMID 41293165, 2025). "Suppression of SLC7A11 significantly inhibited the growth of tumour cells due to increased ferroptosis, while activation of SLC7A11 positively correlated with tumour progression." (PMID 41451920, 2025). "MiR-5096 inhibits tumor growth in breast cancer cells by targeting SLC7A11, reducing GSH levels and increasing ROS and lipid ROS levels." (PMID 40403492, 2025). "Functional studies reveal that BAP1 reduces H2Aub levels at the SLC7A11 promoter through its enzymatic activity, thereby inhibiting cystine uptake and inducing ferroptosis—a process demonstrating significant tumor suppression in animal models." (PMID 40919133, 2025). "Overexpression of SLC7A11 can promote tumor growth by inhibiting ferroptosis and evade ferroptosis through post-transcriptional mechanisms." (PMID 40007539, 2025). "Analyses of The Cancer Genome Atlas (TCGA) and Gene Expression Omnibus (GEO) databases revealed significantly elevated expression of SLC7A11 in tumor tissues compared to normal tissues." (PMID 40427734, 2025). "Tumor cells frequently overexpress the cystine/glutamate antiporter SLC7A11 to facilitate excessive cystine uptake for glutathione (GSH) biosynthesis—an essential antioxidant defense and contributor to chemoresistance." (PMID 41281650, 2025). "METTL3 plays a dual role in LUAD, acting as a tumour promoter and ferroptosis inhibitor through stabilisation of SLC7A11 m6A modification." (PMID 39865544, 2025). "Inhibiting SLC3A2 and SLC7A11 can decrease intracellular cystine levels in tumor cells, increasing their sensitivity to ferroptosis induction." (PMID 39273090, 2024). "Wang and colleagues have recently reported that LSH is able to enhance the expression of SLC7A11 by binding to its promoter region, playing a critical role in tumor development by inhibiting ferroptosis." (PMID 39595619, 2024). "In hepatocellular carcinoma, research has found that SOCS2 enhances the ubiquitination and degradation of SLC7A11, thereby promoting ferroptosis in tumor cells and increasing radiosensitivity." (PMID 39769177, 2024). "SLC7A11 also affects the nutrient dependence of tumor cells through glutamine backfilling and GLS dependence." (PMID 39040097, 2024). "Compared with the pcDNA3.1-NC group, increased TRAIL reduced the expression of FTH1, GPX4, and SLC7A11 in tumor tissues (P < 0.01)." (PMID 38383815, 2024). "This suggests that the overexpression of LINC00896 prevents miRNA from inhibiting SLC7A11 expression, thereby promoting tumor progression." (PMID 38534739, 2024). "Interferon gamma (IFN-γ) secreted by activated CD 8+ cells down-regulates SLC7A11 leading to ferroptosis in tumor cells." (PMID 39670103, 2024). "In vivo experiments and correlation analysis based on clinical specimens further confirmed that TRIM7 inhibited tumor growth through suppressing SLC7A11/GPX4 axis." (PMID 38509147, 2024). "The recent study revealed a significant reliance on NADPH and glucose in tumor cells expressing high levels of SLC7A11, thereby questioning the conventional understanding of SLC7A11 as a promoter of cancer." (PMID 39040097, 2024).